EPHB3 (EPH receptor B3)
Diseases named in the same sentence as EPHB3 in open-access papers (continued):
Sharing a sentence is not in itself a finding about the gene and the disease.
glioblastoma (5 papers, 2019 to 2023). The most malignant astrocytic tumor (WHO grade IV). "The results revealed that EphA2, EphB2, EphB3, and EphB4 were significantly upregulated, while EphA4 and EphB6 were significantly downregulated in glioblastoma than normal brain tissues, respectively." (PMID 37146061, 2023). "Our finding that miR-29a increases growth and invasion by downregulating PTEN, EphB3 and Sox4 in glioblastoma indicates the presence of a coordinated program promoting tumor aggressiveness." (PMID 30683134, 2019). "In PTEN-deficient glioblastoma cells, however, miR-29a nevertheless activates AKT by downregulating the metastasis suppressor, EphB3." (PMID 30683134, 2019). "Our finding that miR-29a decreases expression of both PTEN and EphB3 in glioblastoma raised the possibility that miR-29a regulates a coordinated invasion program in glioblastoma." (PMID 30683134, 2019). "Moreover, siRNA-mediated knockdown of EphB3 in LN229 glioblastoma cells increased AKT phosphorylation and activation." (PMID 30683134, 2019). "Thus, miR-29a decreases EphB3 expression to activate AKT in glioblastoma." (PMID 30683134, 2019). "miR-29a downregulates PTEN, EphB3 and SOX4 expression to activate a complex post-transcriptional program of growth and invasion in glioblastoma." (PMID 30683134, 2019). "Taken together, these data suggest that miR-29a decreases EphB3 to activate the PI3K/AKT and Wnt pathways, thereby promoting proliferation and survival in glioblastoma cells." (PMID 30683134, 2019). "Down‐regulation of EPHB3 and TNFAIP3 activated the PI3K/Akt and NF‐κB signaling pathway, enhanced proliferation and inhibited apoptosis of glioblastoma cells, and eventually enhanced the TMZ resistance in glioblastoma." (PMID 35582627, 2022). "In addition, a study has shown that miR-29a increases growth and invasion in glioblastoma; this program involves not only coactivation of the AKT/PI3K and Wnt pathways through the downregulation of PTEN and EphB3, but also the activation of a newly discovered Sox4/Hic5 invasion pathway." (PMID 33014873, 2020).
non-small cell lung carcinoma (5 papers, 2011 to 2023). A group of at least three distinct histological types of lung cancer, including non-small cell squamous cell carcinoma, adenocarcinoma, and large cell carcinoma. "Ephrin type-B receptor 3 (EphB3) expression has been found to be higher in non-small cell lung cancer as well as associated with metastasis." (PMID 30139389, 2018). "On the other hand, in non-small cell lung cancers, EPHB3 overexpression leads to decreased AKT activity, which suppresses tumor cell migration and metastasis." (PMID 32294981, 2020). "EphB3 is overexpressed in non-small-cell lung cancer and promotes tumor metastasis in a kinase-independent manner." (PMID 22035226, 2011). "However, in non-small cell lung cancer, RACK1 mediates the assembly of the RACK1–PP2A–Akt signaling complex in response to EphB3 activation, leading to decreased Akt phosphorylation and the inhibition of cell migration." (PMID 37296580, 2023).
prostate carcinoma (5 papers, 2018 to 2025). A carcinoma that arises from epithelial cells of the prostate gland. "EphrinB2 ligand expressed on prostate CAFs can interact with the EphB3/4 receptors on the surface of prostate cancer cells to activate Cdc42 signaling and increase the invasive potential of PC-3 cells in vitro." (PMID 36671452, 2022). "For instance, elevated levels of EphB3 and EphB4 receptors on prostate cancer cells has been shown to impair contact-inhibition locomotion in fibroblast co-cultures assays." (PMID 36671452, 2022). "For example, for metastatic prostate cancer cells, it has been shown that they invade fibroblasts dependent on EphB3 and EphB4 signaling and activation of Cdc42." (PMID 34502237, 2021). "The prostate cell line panel has indicated a decrease in EphB2 with elevations in both EphB3 and EphB6 in some prostate carcinoma cells compared to normal prostate epithelial cells." (PMID 29682554, 2018). "Microarray and RT-PCR analysis of prostate cancer tissue have also identified differential expression of EphB3." (PMID 29682554, 2018). "Upon heterotypic collisions between prostate cancer cells and fibroblasts, the CIL response was dramatically decreased owing to enriched levels of EphB3 and EphB4 in the prostate cancer cells." (PMID 30154457, 2018). "We also examined the expression of other EphB receptor family members (EphB1, EphB2, EphB3) with no change in normal and prostate cancer." (PMID 40044981, 2025).
breast carcinoma (4 papers, 2014 to 2021). "In addition, high EPHB3 levels are associated with poor survival in breast cancer patients, which supports its oncogenic and pro-metastatic properties." (PMID 34771489, 2021). "Breast cancer cell lines known to express the target antigens ErbB2, EphA2, EphB3, and CD44 with high and low levels were stained with the identified phage mAbs and evaluated by fluorescence microscopy." (PMID 25353955, 2014).
ependymoma (2 papers, 2009 to 2024). A WHO grade II, slow growing tumor of children and young adults, usually located intraventricularly. "Increased EPHB3 levels have also been reported in ependymoma cells." (PMID 38612645, 2024). "In 2005, research identified the overexpression of ephrin-A3, ephrin-A4, EPHB2, EPHB3, and EPHB4 in ependymoma tumor cells, either from frozen or formalin-fixed tumor samples, but the clinical impact remains unclear." (PMID 38612645, 2024).
medulloblastoma (2 papers, 2024 to 2025). A malignant, invasive embryonal neoplasm arising from the cerebellum. "Similar to EphB3, EphB4 expression is downregulated in migratory medulloblastoma cells, suggesting an inverse relationship with invasion and a possible association with stem-like tumor phenotypes." (PMID 41200151, 2025). "This downregulation is further supported by decreased EphB3 mRNA levels across multiple medulloblastoma cell lines (DAOY, Res-220, Res-256, UW-426, UW-473, and UW-402) relative to fetal brain and adult cerebellum." (PMID 41200151, 2025). "EPHB1 and EPHB3 are overexpressed in rhabdomyosarcoma tumor cells, while EPHB2 high-level expression has been reported in medulloblastoma tumor tissue samples, in NF2-deficient meningioma cell lines, and rhabdomyosarcoma tumor cells." (PMID 38612645, 2024). "EphB3 expression is consistently downregulated in medulloblastoma." (PMID 41200151, 2025).
neuroblastoma (2 papers, 2014 to 2024). Neuroblastoma (NB) is the most common solid, extracranial childhood tumor. "Next, EphB3 and the EphB3 D849N mutant were transiently overexpressed in the human neuroblastoma cell line SY5Y in the presence and absence of eB3-Fc." (PMID 24810043, 2014).
viral infection (2 papers, 2016 to 2022). "As an important initiation transactivator, PFV Tas can dramatically increase the transcription of p57Kip2, IGF-II, and EphB3, thereby regulating host cell processing during the process of viral infection." (PMID 35132916, 2022).
Anophthalmia (1 paper, 2023). Absence of the globe or eyeball. "We identified a second heterozygous VUS, EPHB3(NM_004443.4):c.1259G>A (p.Arg420His) in a male proband with HPO in terms of autism, microphthalmia, seizures, and true anophthalmia." (PMID 36830662, 2023).
Arthritis (1 paper, 2024). Inflammation of a joint. "On day 34, there were no significant variations in the proportions of most of the immune cell subsets analyzed between the EphB3-deficient mice which developed arthritis, and those that remained healthy." (PMID 38558087, 2024). "Furthermore, attempts to induce arthritic lesions after chicken type II collagen administration fail totally in EphB2-deficient mice whereas all WT and half of the immunized EphB3−/− mice develop a typical collagen-induced arthritis." (PMID 38558087, 2024). "A similar condition occurred in EphB3−/− mice, but only 36% of mutants developed arthritis (insert)." (PMID 38558087, 2024). "Results will be compared with those of healthy WT (WT non-CIA) and EphB3−/− mice (EphB3−/− non-CIA), as well as with WT mice developing arthritis (WT CIA)." (PMID 38558087, 2024).
atherosclerosis (1 paper, 2021). A disease characterized by the build-up of fatty material and calcium deposition in the arterial wall resulting in partial or complete occlusion of the arterial lumen. "EPHB3 is also involved in immune cell activation and trafficking and is related to the pathogenesis of various diseases, including immune-mediated conditions, cancer, atherosclerosis, and central nervous system diseases." (PMID 33921847, 2021).
brain injury (1 paper, 2014). Acute and chronic (see also brain INJURIES, CHRONIC) injuries to the brain, including the cerebral hemispheres, CEREBELLUM, and brain STEM. "Here, we examined whether EphB3 mediates cell death in the adult forebrain following traumatic brain injury and whether ephrinB3 infusion could limit this effect." (PMID 24810043, 2014). "Together, these findings suggest that EphB3 may mediate neuronal cell death through a novel dependence receptor mechanism, which can be prevented with ephrinB3 treatment following brain trauma." (PMID 24810043, 2014).
cardiomyopathy (1 paper, 2025). A disease of the heart muscle or myocardium proper. "Although IL1R1 has been implicated in aging-associated cardiomyopathy, FCGR3A, EphB3 and Serpin F1 have not been shown to have any effects." (PMID 41020515, 2025).
colitis (1 paper, 2020). Inflammation of the colon. "In an azoxymethane/dextran sulfate sodium-induced, colitis-associated, CRC model, EPHB3 expression increased along with tumor development." (PMID 32294981, 2020).
coloboma (1 paper, 2023). An abnormality in which a part of a structure in one or both eyes is missing. "All our conserved OFC genes, including the two novel MAC candidates, EMX2 and EPHB3, should be considered for further genetic and molecular analyses based on their gene expression profiles during eye development and the presence of coloboma and microphthalmia phenotypes in animal models." (PMID 36830662, 2023).
craniosynostosis (1 paper, 2023). Craniosynostosis is defined as the premature fusion of one or more cranial sutures leading to secondary distortion of skull shape resulting in skull deformities with a variable presentation. "Therefore, Ephb2 may work together with Ephb3 as seen during palate formation but downstream of Ephb3 during craniosynostosis." (PMID 37378024, 2023).
dengue (1 paper, 2024). "We observed that EPHB3, ERBB2, FGFR2, IGF1R, and RET are upstream regulators both of kinases shown to be important in previous dengue research and of kinases predicted by KiR." (PMID 38585651, 2024).
diabetic retinopathy (1 paper, 2021). "The vascular density in diabetic retinopathy tissues was significantly greater than that seen in retinopathy of prematurity tissues, where there was also much less expression of ephrinB2, EphB2, and EphB3 (25%, 70%, and 45% respectively)." (PMID 34201393, 2021).
epilepsy (1 paper, 2017). A brain disorder characterized by episodes of abnormally increased neuronal discharge resulting in transient episodes of sensory or motor neurological dysfunction, or psychic dysfunction. "In mouse model, it has been confirmed that the activation of EPH receptor associated genes, like EPHB3, contributes to the onset of epilepsy." (PMID 28255556, 2017).
epithelial colon tumors (1 paper, 2017). "As a result, we examined in detail the impact of FOXA factors on enhancer regions at the CDH1, CDX2 and EPHB3 genes which are among the signature genes of epithelial colon tumors and which are downregulated in Snail1-expressing LS174T cells." (PMID 29155818, 2017).
head and neck squamous cell carcinoma (1 paper, 2021). A squamous cell carcinoma that arises from any of the following anatomic sites: lip and oral cavity, nasal cavity, paranasal sinuses, pharynx, larynx, and salivary glands. "In the colorectal cancer mice model, EphB3 expression was also found to be increased along with tumor development and coamplified with PIK3CA in head and neck squamous cell carcinoma (HNSCC)." (PMID 34959648, 2021).
liver fibrosis (1 paper, 2023). "However, our preliminary study showed that EphB1 was the only NEDD8-conjugated protein among EphB1 to EphB3 in activated HSCs, suggesting that the activation of EphB1 and the way it functions may be different from EphB2 in liver fibrosis." (PMID 36834826, 2023).
metastatic cancer (1 paper, 2020). A carcinoma which has spread from the original site of growth to another anatomic site. "To determine the changes in EPHB3 expression during invasion and lymph node metastasis, we compared H-scores in three regions of each CRC case: a superficial fungating region, the invasive fronts, and metastatic cancer cells in the lymph nodes." (PMID 32294981, 2020).
Obesity (1 paper, 2022). Accumulation of substantial excess body fat. "Seven of the genes were downregulated by obesity and reversed by VSG specific weight loss including Ido1, Aldoc, Tmem125, Dgki, Slc7a4, Msc, and Ephb3, while four were inversely regulated with obesity elevating Klhl5, Nek6, Arhgap20, and Hp." (PMID 35775614, 2022).
Ovarian cyst (1 paper, 2006). The presence of one or more cysts of the ovary. "Hence EphA1, EphA2, EphB2, EphB3, EphB6, ephrin A1, ephrin A5 and ephrin B1 were selected for further analysis in an additional fourteen tumor samples, one ovarian cyst and one ovarian adenoma." (PMID 16737551, 2006).
pancreatic cancer (1 paper, 2024). "In this study, we found a significant association between pancreatic cancer driver genes, EGF, EPHB3, and POTEF, and original.glrlm.RunVariance." (PMID 38811597, 2024).
peripheral nerve injury (1 paper, 2021). Injury to a peripheral nerve. "Moreover, EPHB3 expressed in vascular endothelial cells regulates angiogenesis in peripheral nerve injury." (PMID 33921847, 2021).
retinal diseases (1 paper, 2021). "EphrinA1, ephrinA4, ephrinA5, EphA2, EphA7, ephrinB2, EphB3, and EphB4 seem to be the most important in the context of retinal diseases." (PMID 34201393, 2021).
rhabdomyosarcoma (1 paper, 2024). A rare aggressive malignant mesenchymal neoplasm arising from skeletal muscle. "An increased expression of EPHs (EPHB1, EPHB2, EPHB3, and EPHB4) and their ephrin ligands (ephrin-B1 and ephrin-B2) has been implicated in promoting angiogenesis and tumor progression in rhabdomyosarcoma." (PMID 38612645, 2024).
spinal cord injury (1 paper, 2015). Penetrating and non-penetrating injuries to the spinal cord resulting from traumatic external forces (e.g., WOUNDS, GUNSHOT; WHIPLASH INJURIES; etc.). "Spinal cord injury (SCI) is associated with tissue damage, cellular loss and disturbances in EphB3-ephrinB3 protein balance acutely (days) after the initial impact creating an environment for a dependence receptor-mediated cell death to occur." (PMID 26469970, 2015).
tumor (46 papers, 2006 to 2025). "Depletion of EPHB3 promoted cell growth and invasion in vitro while EphB3 downregulation is associated with increased tumor size, invasion, clinical staging, lymphatic metastasis, and poor prognosis." (PMID 39839790, 2024). "EphB1 and EphB3 act as tumor suppressors, and their low expression is associated with metastasis and a poor prognosis." (PMID 39839790, 2024). "Subsequent studies showed that that ephrin-B1 controls the distribution and spread of EphB2- and EphB3-expressing tumour cells in the colon, which is overcome during tumour progression by the loss of EphB expression." (PMID 36830852, 2023). "Statistical analysis linked EPHB3 expression to tumor differentiation, lymphovascular invasion, TNM stage, microsatellite instability and better OS." (PMID 34445116, 2021). "Using tumor samples from a large cohort of CRC patients we demonstrated that EPHB3 expression is positively associated with less advanced tumor stages and therefore better clinical outcomes." (PMID 32294981, 2020). "qPCR analysis revealed reduced EphB3 levels in migratory cells compared to central tumor regions, and in low vs. high self-renewing tumor spheres, suggesting a context-dependent, potentially suppressive role within the Eph-ephrin axis." (PMID 41200151, 2025). "Conversely, EphB3 overexpression suppresses these malignant traits by downregulating this pathway, indicating its tumor-suppressive role and highlighting its potential as a diagnostic and therapeutic target." (PMID 41200151, 2025). "In this sense, cells expressing EphB3 aggregate and adhere, leading to restricted dissemination of EphB-expressing tumor cells in ephrin-B1-positive territories and consequent tumor compartmentalization." (PMID 38651144, 2024). "For example, in HT-29 cells, EPHB3 overexpression increased cell-cell contact and suppressed tumor growth by reorganizing the cytoskeleton and inducing functional changes that favored mesenchymal-epithelial transition (MET)-the opposite process of EMT." (PMID 38651144, 2024). "In contrast, the downregulation of EphB3 inhibited cell proliferation and migration and suppressed in vivo tumour growth and metastasis." (PMID 36830852, 2023). "EphB3 was also shown to be more abundant in NSCLC samples than in normal tissues, and its expression was associated with tumour growth and metastasis." (PMID 36830852, 2023). "The blockage of EphB2 and EphB3 signaling accelerated the carcinogenesis process, indicating their tumor suppressive function." (PMID 35269901, 2022). "Overexpression of EphB3 in non-small-cell lung cancer was reported to increase metastasis via increasing the tumor migratory capabilities, which in turn increases the tumor survival." (PMID 34959648, 2021). "In human CRC cells, lesions in Notch signaling impair EPHB3 enhancer function, while activation of Notch can induce EPHB3 expression concomitant with a tumor suppressive response." (PMID 33525395, 2021). "The tumour-suppressor function of EphB2 and EphB3 is thought to be reliant on their ability to compartmentalise tumour cells, which involves E-cadherin-mediated adhesion." (PMID 33430066, 2021). "Mucin production (p = 0.042) and elevated levels of tumor infiltrating lymphocytes ((TIL) > 8 per high power field) (p < 0.001) were more frequently observed in EPHB3-positive CRCs." (PMID 32294981, 2020). "Further studies are required to identify the molecular mechanisms (including signaling pathways) that govern EPHB3 silencing at the invasive tumor fronts." (PMID 32294981, 2020). "EPHB3 is downregulated in advanced stages of human CRC, which suggests that EPHB3 functions as a tumor suppressor in this context." (PMID 32294981, 2020). "Namely, a substantial reduction of EPHB3 expression was observed in the budding cancer cells at the invasive tumor fronts, which was more extensive than E-cadherin downregulation." (PMID 32294981, 2020).